SFRP2 (secreted frizzled related protein 2)
Diseases named in the same sentence as SFRP2 in open-access papers (continued):
Sharing a sentence is not in itself a finding about the gene and the disease.
osteosarcoma (15 papers, 2016 to 2024). A usually aggressive malignant bone-forming mesenchymal neoplasm, predominantly affecting adolescents and young adults. "While we believe our studies provide significant contributions towards understanding metastatic mechanisms for osteosarcoma, further studies are warranted to investigate direct downstream molecular mechanisms associated with sFRP2 expression." (PMID 27821163, 2016). "Enhanced Wnt signaling by methylation-mediated loss of SFRP2 promoted osteosarcoma cell invasion." (PMID 28665975, 2017). "High expression of SFRP2 has been observed in osteosarcoma cells, where its upregulation promotes cell proliferation and migration, endowing them with metastatic potential." (PMID 39850884, 2024). "Secreted frizzled-related protein 2 (SFRP2) promotes the migration/invasion of metastatic osteosarcoma (OS) cells and tube formation by endothelial cells." (PMID 34070758, 2021). "Given the importance of developing prognostic biomarkers to predict response to therapy, additional studies evaluating the potential of SFRP2 as a clinical prognostic or predictive biomarker of response in osteosarcoma patients are warranted." (PMID 34070758, 2021). "Meanwhile, secreted Fzd-related protein 2 (sFRP2) was highly expressed in osteosarcoma patients and inversely correlated with survival." (PMID 34130697, 2021). "We conclude that SFRP2-targeted immunotherapy reduces the growth of metastatic osteosarcoma, not only through a direct antitumor and antiangiogenic effect but also by impacting the immune system." (PMID 34070758, 2021). "This compelling evidence supports the emergence of SFRP2 as a potential therapeutic target for metastatic osteosarcoma." (PMID 34070758, 2021). "For example, overexpression of SFRP2 promotes migration, invasion and metastasis of osteosarcoma cells in vitro and in vivo." (PMID 34852024, 2021). "To test the efficacy of SFRP2-targeting immunotherapy on metastatic osteosarcoma, we used two genetically engineered murine cell lines, RF420 and RF577." (PMID 34070758, 2021). "Our studies provide insights into the functional role of sFRP2 within osteosarcoma tumor development and metastasis." (PMID 27821163, 2016). "Molecular analysis of a metastatic genetically engineered mouse model of osteosarcoma identified enhanced expression of Secreted Frizzled-Related Protein 2 (sFRP2), a putative regulator of Wnt signaling within metastatic tumors." (PMID 27821163, 2016). "We further examined the relative expression of sFRP2 in human osteosarcoma tumor specimens and cell lines." (PMID 27821163, 2016). "After demonstrating that enhanced sFRP2 expression contributes towards OS migratory and invasive potential in vitro, we next investigated the effects of reducing sFRP2 in highly metastatic osteosarcoma cells." (PMID 27821163, 2016). "In our studies, we have demonstrated that sFRP2 has enhanced expression in metastatic mouse and human osteosarcomas." (PMID 27821163, 2016). "We expressed sFRP2 in low-metastatic mouse and human osteosarcoma cell lines, RF43 (designated as sFRP2/RF43) and HOS (designated as sFRP2/HOS)." (PMID 27821163, 2016). "Further studies are warranted to investigate the exact mechanisms of action for sFRP2 and its regulation of metastatic pathways for osteosarcoma." (PMID 27821163, 2016). "Exploration of sFRP2 expression in human osteosarcoma revealed enhanced expression compared to mesenchymal stem cells (MSCs)." (PMID 27821163, 2016). "The upregulation of COL11A1 and SFRP2 has been reported in human osteosarcoma." (PMID 35456486, 2022). "The oncogenic role of SFRP2 is proved in osteosarcoma and renal cancer." (PMID 34852024, 2021).
osteosarcoma (continued). "In the future, clinical trials will determine whether anti-SFRP2 therapy will be safe and efficacious for osteosarcoma in humans." (PMID 34070758, 2021). "Similarly, SFRP2 mRNA was decreased in osteosarcoma cell lines compared to primary osteoblast cells." (PMID 33140138, 2021). "Similarly, SFRP2 expression was significantly higher in osteosarcoma tumors compared to mesenchymal stem cells." (PMID 33140138, 2021). "Additionally, growing evidence strongly supports the contribution of SFRP2 to osteosarcoma metastases." (PMID 34070758, 2021). "sFRP2 overexpression could induce angiogenesis and drive osteoblast precursors into osteosarcoma phenotype, while knockdown of sFRP2 impaired its metastatic and invasive behavior." (PMID 34130697, 2021). "However, sFRP2, another Wnt inhibitory factor, also facilitates the infiltration and metastasis of osteosarcoma." (PMID 31698687, 2019). "After identifying and confirming differential expression of sFRP2 in mouse and human metastatic OS, and its clinical relevance for patients with bone sarcomas, our goal was to elucidate the phenotypic effects of sFRP2 on osteosarcoma." (PMID 27821163, 2016). "Studies into if sFRP2 could alter the differentiation or stemness of osteosarcoma cells would also be interesting to investigate." (PMID 27821163, 2016). "However the role of sFRP2 in mesenchymal tumor biology, such as osteosarcoma, remains to be elucidated." (PMID 27821163, 2016). "Investigations into additional signaling cascades could provide novel insights into the direct role of sFRP2 and metastatic mechanisms for osteosarcoma." (PMID 27821163, 2016). "While future studies further investigating the molecular mechanisms contributing towards this sFRP2-dependent phenotype are needed, our studies clearly provide evidence that aberrant expression of sFRP2 can contribute to the invasive and metastatic potential for osteosarcoma." (PMID 27821163, 2016). "SFRP2 is significantly upregulated in the primary bone tumor from patients with metastatic disease compared to tumors from patients with only localized disease, and within the highly metastatic human osteosarcoma cell line 143B compared to its paired cell line HOS that has low metastatic potential." (PMID 27821163, 2016). "Contrary to SFRP2, which facilitates infiltration and the metastasis of osteosarcomas, SFRP3 is downregulated in osteosarcoma patients at the local and systemic levels and upregulated in bone marrow multiple myeloma samples with advanced lytic bone disease (LBD) as compared to no/limited LBD." (PMID 35052478, 2022). "While overexpression of SFRP2 in osteosarcoma cells did not significantly affect primary tumor growth, a larger number of lung metastases occurred." (PMID 33140138, 2021). "However, the role of sFRP2 in osteosarcoma development and progression has not been well elucidated." (PMID 27821163, 2016).
breast tumor (13 papers, 2006 to 2024). "SHC2, LPL, PCK1, and KRT6B were all under-expressed, and only SFRP2 was highly expressed in the breast tumor." (PMID 38791477, 2024). "The decreased expression is consistent with previous studies showing downregulation of overall SFRP1 and SFRP2 expression in breast tumors through DNA promoter hypermethylation." (PMID 37091166, 2023). "Earlier studies showed that SFRP2 expression was elevated in breast tumor endothelium tissues compared to normal tissues." (PMID 37965470, 2023). "SFRP2 was found to promote epithelial cell transformation and to stimulate cell adhesion to the extracellular matrix in breast tumours, which consequently promotes resistance to apoptosis." (PMID 30154364, 2018). "In breast tumors, the interaction between the tumor cells and the AT1 cells activates the Secreted Frizzled-Related Protein 2 (SFRP2) protein, resulting in fibronectin fibril formation and tumor cell survival." (PMID 39682261, 2024). "Whether SFRP2 methylation is already present in benign and earlier premalignant lesions such as atypical hyperplasia and carcinoma in situ, like it was recently reported for the 14-3-3-σ gene, will be of particular importance in regard of early breast tumor detection." (PMID 18990230, 2008). "In primary breast tumours, methylation frequencies of SFRP1, SFRP2, SFRP5 and DKK1 were 40, 77, 71 and 19%, respectively." (PMID 18283316, 2008). "Antagonizing SFRP2 has previously been shown to induce apoptosis in endothelial cells and breast tumor cells, but the effects on T-cells have not been evaluated." (PMID 34070758, 2021). "However, it is worth noting that to our knowledge this is the first time that promoter methylation in CCDC8, HOXD3, PCDH8, PENK, STAT3, SFRP2 and WIFI has been described in primary breast tumours." (PMID 26052355, 2015). "Moreover, a few genes involved in modulation of the extracellular matrix (ADAMTS4, MMP1, MMP3, and angiogenesis (MFAP5, SFRP2, SRPK1, VEGF, and CHI3L1) were found to be expressed at higher levels in the primary breast tumors compared with the bone metastases." (PMID 23174366, 2012).
glioma (13 papers, 2016 to 2025). A benign or malignant brain and spinal cord tumor that arises from glial cells (astrocytes, oligodendrocytes, ependymal cells). "The potential functions of SFRP2 in glioma were evaluated by loss-of-function assays and gain-of-function assays in glioma cell lines." (PMID 34852024, 2021). "In summary, we found that SFRP2 was downregulated in radiotherapy treated glioma patients, and low SFRP2 expression was associated with advanced tumor stage, larger tumor size, radioresistance and poor survival." (PMID 34852024, 2021). "We found that SFRP2 was evidently downregulated in radiotherapy treated glioma patients, and low SFRP2 expression was associated with higher tumor stage." (PMID 34852024, 2021). "The potential functions of SFRP2 in glioma cells were evaluated by loss-of-function assays." (PMID 34852024, 2021). "SFRP2, an inhibitor of the Wnt signaling pathway, affects glioma cell proliferation, migration, and survival through Wnt signal regulation." (PMID 40535771, 2025). "CRISP/Cas9-mediated SFRP2 knockdown promoted soft agar colony formation, cancer stemness and radioresistance of glioma cells, while increased SFRP2 expression exhibited opposite effects." (PMID 37239828, 2023). "SFRP2 was downregulated in radiotherapy-treated glioma patients, and low SFRP2 expression was correlated with advanced tumor stage and poor prognosis." (PMID 37239828, 2023). "The downregulation of SFRP2 facilitates the stemness of glioma by activating Wnt/β-catenin signaling." (PMID 35741755, 2022). "SFRP2 knockdown activated Wnt/β-catenin signaling in glioma cells, while overexpression of SFRP2 inhibited Wnt/β-catenin activation." (PMID 34852024, 2021). "SFRP2 is frequently hypermethylated in glioma patients, and analysis of TCGA data indicates that SFRP2 is one of the most downregulated genes in radiotherapy treated glioma patients." (PMID 34852024, 2021). "Knockdown of SFRP2 promoted soft agar colony formation, cancer stemness and radioresistance of glioma cells, while overexpression of SFRP2 showed opposite effects." (PMID 34852024, 2021). "Our results for the first time demonstrated that SFRP2 was involved in radioresistance of glioma patients." (PMID 34852024, 2021). "Above all, our data indicated that forced SFRP2 expression suppressed soft agar colony formation, cancer stemness and radioresistance of glioma cells." (PMID 34852024, 2021). "We found that SFRP2 was downregulated in radiotherapy-treated glioma patients, and low SFRP2 expression was correlated with advanced tumor stage and poor prognosis." (PMID 34852024, 2021). "In tumor subgroups based on SOX2 and SFRP2 transcript levels in the TCGA and The Chinese gliomas genome atlas (CGGA) glioblastoma datasets, the respective SFRP2high/SOX2low subgroups were enriched with mesenchymal subtype tumors." (PMID 34021259, 2021). "SFRP2 knockdown promoted soft agar colony formation, cancer stemness and radioresistance of glioma cells, while overexpression of SFRP2 exhibited contrary effects." (PMID 34852024, 2021). "SFRP2 is a key regulator of Wnt/β-catenin pathway, thus we evaluated the expression of Wnt pathway related genes in glioma patients." (PMID 34852024, 2021). "In our study, we found that SFRP2 was the most significantly downregulated gene in radiotherapy treated glioma patients." (PMID 34852024, 2021). "The correlation between SFRP2 expression and clinicopathological characteristics of glioma patients was also evaluated." (PMID 34852024, 2021). "In the present study, we found that SFRP2 acted as an antagonist for canonical Wnt/β-catenin signaling in glioma cells." (PMID 34852024, 2021). "Collectively, our results indicated that SFRP2 knockdown promoted soft agar colony formation, cancer stemness and radioresistance of glioma cells in vitro and in vivo." (PMID 34852024, 2021).
glioma (continued). "In the present study, we found that SFRP2 was downregulated in radiotherapy treated glioma patients and correlated with advanced tumor stage and poor survival." (PMID 34852024, 2021). "Together, these findings present SFRP2 as a SOX2-antagonist with the capacity to induce a mesenchymal subtype transition in glioma cells located in vascular tumor areas, highlighting its role in glioblastoma tumor evolution and intratumoral heterogeneity." (PMID 34021259, 2021). "CRISP/Cas9-meidated SFRP2 knockdown promoted soft agar colony formation, cancer stemness and radioresistance of glioma cells, while enforced SFRP2 expression exhibited opposite effects." (PMID 34852024, 2021). "In the present study, we found that SFRP2 was downregulated in radiotherapy treated glioma patients, and low SFPR2 expression was correlated with advanced tumor stage and poor prognosis." (PMID 34852024, 2021). "Though a previous report suggest that SFPR2 promotes clonogenicity and tumor growth of glioma cells, accumulated evidences reveal a tumor suppressive role of SFRP2 in glioma." (PMID 34852024, 2021). "SFRP2 knockdown activated Wnt/β-catenin signaling in glioma cell lines, while overexpression of SFRP2 inhibited Wnt/β-catenin activation." (PMID 34852024, 2021). "Collectively, our data indicated that pharmacological inhibition of Wnt/β-catenin signaling abrogated the effects of SFRP2 knockdown on soft agar colony formation, cancer stemness and radioresistance of glioma cells." (PMID 34852024, 2021). "In the present study, we focused on SFRP2 because it ranked the first in the downregulated genes, and previous studies indicate that SFRP2 acts as a tumor-suppressor in glioma and regulates Wnt signaling activation in various cancers." (PMID 34852024, 2021). "In the present study, we overexpressed SFRP2 in glioma cells and evaluated for the influence on colony formation, cancer stemness and radioresistance." (PMID 34852024, 2021). "Low SFRP2 expression was apparently correlated with poor overall-survival and progression-free survival of glioma patients." (PMID 34852024, 2021). "In the present study, we aimed to explore the potential function of SFRP2 in tumorigenesis and radioresistance of glioma." (PMID 34852024, 2021). "When comparing subgroups within the same cancer type, expression of SFRP2 was found to be lower in high grade-, as compared to low grade glioma." (PMID 33140138, 2021). "Of note, XIST showed lower expression levels in DA tumors (versus some AA and GBM), while FSTL5 and SFRP2 expression was greater in DA vs AA gliomas." (PMID 32647207, 2020). "On the other hand, SFRP2 in glioma is an exception: It is the only cancer where SFRP2 expression negatively correlates with EMT and angiogenesis gene sets." (PMID 28218291, 2017). "In glioma, high SFRP4 expression is strongly associated with poor outcomes (HR = 3.93 [2.27–6.81], p < 0.0001), while high SFRP2 expression is strongly associated with favourable outcomes (HR = 0.16 [0.09–0.28], p < 0.0001)." (PMID 28218291, 2017). "Sfrp1 and Sfrp2 are produced by long-term and ex vivo malignant glioma cells and are thought to act as survival and proliferation-promoting factors." (PMID 27048460, 2016). "Moreover, SFRP2 knockdown activated Wnt/β-catenin signaling in glioma cell lines, while overexpression of SFRP2 inhibited Wnt/β-catenin activation." (PMID 37239828, 2023). "Furthermore, SFRP2 knockdown promoted soft agar colony formation, cancer stemenss and radioresistance of glioma cells, while overexpression of SFRP2 showed contrary effects." (PMID 34852024, 2021). "Our results for the first time demonstrated that SFRP2 was involved in radioresistance of glioma, and inhibition of Wnt/β-catenin signaling might increase the effect of radiotherapy in glioma patients." (PMID 34852024, 2021).